DET1 (DET1 partner of COP1 E3 ubiquitin ligase)
Description:
Component of the E3 ubiquitin ligase DCX DET1-COP1 complex, which is required for ubiquitination and subsequent degradation of target proteins. The complex is involved in JUN ubiquitination and degradation.
Synonyms: FLJ10103
Tractability: PROTAC: ubiquitination databases record sites on it.
Gene: Protein-coding gene on chromosome 15 (88,494,440 to 88,547,321, reverse strand). Ensembl gene ENSG00000140543.
Subcellular location: Nucleus
Subcellular location (Human Protein Atlas): Microtubules; Cytokinetic bridge; Nucleoplasm
Pathways (Reactome):
Immune System: Antigen processing: Ubiquitination & Proteasome degradation
Gene Ontology:
Molecular function: protein binding; protein-containing complex binding; ubiquitin protein ligase binding; ubiquitin-like ligase-substrate adaptor activity
Biological process: positive regulation of proteasomal ubiquitin-dependent protein catabolic process; protein ubiquitination; protein-containing complex assembly
Cellular component: Cul4-RING E3 ubiquitin ligase complex; Cul4A-RING E3 ubiquitin ligase complex; cullin-RING ubiquitin ligase complex; nucleus
Genetic constraint (gnomAD): Loss-of-function variants: 22 observed, 45.4 expected, observed/expected ratio (o/e) 0.48, 90% interval 0.34 to 0.69. The upper end of that interval is the gene's LOEUF score, 0.69, which puts it in group 2 of 6, group 1 being the genes least tolerant of losing a copy. Missense variants: 713 observed, 743.52 expected, observed/expected ratio (o/e) 0.96, 90% interval 0.9 to 1.02. Synonymous variants: 315 observed, 280.92 expected, observed/expected ratio (o/e) 1.12, 90% interval 1.02 to 1.23.
Homologues: Orthologues: chimpanzee DET1 (100% identical), macaque DET1 (99% identical), pig DET1 (99% identical), guinea pig DET1 (99% identical), mouse Det1 (99% identical), dog DET1 (99% identical), rabbit DET1 (97% identical), tropical clawed frog det1 (91% identical), zebrafish det1 (87% identical), rat Det1 (80% identical), Drosophila melanogaster abo (27% identical).
Diseases named in the same sentence as DET1 in open-access papers:
DET1 is named in the same sentence as 10 diseases in open-access papers, as found by Europe PMC text mining. Sharing a sentence is not in itself a finding about the gene and the disease. The quoted sentences say what the papers report.
melanoma (2 papers, 2021 to 2025). A malignant, usually aggressive tumor composed of atypical, neoplastic melanocytes. "We found that patient mutations in COP1 or DET1 inactivated CRL4COP1/DET1 in melanoma cells, stabilized ETV1, ETV4, and ETV5, and conferred resistance to inhibitors of the MAPK pathway." (PMID 40643496, 2025). "De novo activity-attenuating DET1 mutations were identified in two melanoma patients after vemurafenib (RAF inhibitor) treatment, further implicating COP1/DET1 loss as a driver of MAPK inhibitor resistance." (PMID 34066106, 2021).
colorectal cancer (1 paper, 2018). A primary or metastatic malignant neoplasm that affects the colon or rectum. "Moreover, computational analyses of drug response data in a large cancer cell line panel further supports that high DET1 or COP1 expression is correlated with low IC50 values (i.e., sensitivity) for five different MEK inhibitors across a colorectal cancer cell line panel." (PMID 30482246, 2018).
insulinoma (1 paper, 2021). "Depleting COP1 or DET1 leads to the accumulation of ETV5 and, to a mild extent, ETV4 in MIN6 insulinoma cells, whereas co-expressing COP1 and DET1 diminishes ETV5 levels, suggesting that CRL4COP1/DET1 mediates ETV5 degradation, which is further supported by ETV5 stabilization upon MLN4924 treatment." (PMID 33911083, 2021).
lung carcinoma (1 paper, 2022). "While low to no protein detection of DET1 and KHK were observed in both normal and lung cancer tissue." (PMID 36194576, 2022).
cancer (4 papers, 2018 to 2025). A tumor composed of atypical neoplastic, often pleomorphic cells that invade other tissues. "However, ASB2 and HECW2; DET1, GAN, and HERW2 were expressed minimally in the LAML and DLBC cancers, respectively." (PMID 35711821, 2022).
tumor (2 papers, 2013 to 2016). "14,15-EET was less efficient in inducing the transient activation of JNK pathway in tumor cells due to the inhibitory effect of SHIP1 and DET1." (PMID 27270316, 2016). "CUL4-based E3 ligases have been shown to act in tumour suppression, but the DET1/c-Jun link has not been clearly placed in a tumorigenic context or in infection models." (PMID 23637592, 2013).
DET1 also shares sentences with these, for which no sentence is quoted: periodontitis (2 papers); asthma (1); infection (1); lung disease (1).